MAVS (mitochondrial antiviral signaling protein)
Diseases named in the same sentence as MAVS in open-access papers (continued):
Sharing a sentence is not in itself a finding about the gene and the disease.
viral infection (continued). "MAVS regulates cellular apoptosis through interaction with AMBRA1, activates the NF-κB pathway during viral infections to trigger inflammatory factor release, and inhibiting MAVS can significantly reduce inflammatory responses and improve sepsis outcomes." (PMID 40766842, 2025). "Under viral infection conditions, MAVS is known to promote polymerization through CARD-CARD interactions, which recruit IRF3 by IKK-ε and TBK1, leading to the activation of IFN-β." (PMID 40944942, 2025). "The RIG-I MAVS pathway is essential for the early detection of viral infections and the initiation of an effective antiviral immune response." (PMID 40126553, 2025). "Various viruses have evolved immune evasion mechanisms to avoid the activation of MAVS, the treatments for specific viral infections should be adjusted instead of focusing on MAVS itself." (PMID 40842475, 2025). "After viral infection, Stat2 translocates to mitochondria and is degraded by viral disintegration formed by viral proteins and MAVS." (PMID 40076578, 2025). "Upon IAV infection, TRIM31 catalyzes the K63-linked ubiquitination of MAVS and promotes the IFN-I response against virus infection." (PMID 41294327, 2025). "Here, we describe a novel mechanism that links cellular stress to MAVS-dependent immune responses during viral infection." (PMID 40837220, 2025). "Taken together, these results indicate that TXNIP negatively regulates MAVS aggregation during viral infection, thereby attenuating activation of downstream signaling pathways such as TBK1 and IRF3." (PMID 40628121, 2025). "Following viral infection, TRIM31 interacts with MAVS and facilitates K63-linked polyubiquitination at lysine residues 10, 311, and 461 of MAVS." (PMID 39823440, 2025). "Similar reductions were also observed for proinflammatory cytokines Il-6 and Tnfα following viral infection, indicating that MAVS phosphorylation contributes broadly to antiviral cytokine responses." (PMID 40837220, 2025). "Conversely, TXNIP knockout enhanced MAVS aggregation in response to viral infection, further supporting its inhibitory role." (PMID 40628121, 2025). "The downregulation of MAVS is likely to affect NF-κB signalling, as MAVS is involved in the activation of NF-κB during viral infection." (PMID 39940816, 2025). "Previous studies have reported that prolonged MAVS activation, particularly in response to viral infections or RLR stimulation, disrupts mitochondrial dynamics and increases ROS levels in hepatocytes and epithelial cells, ultimately impairing bioenergetics." (PMID 40429828, 2025). "During viral infection, RIG-I identifies viral RNA, triggering the association between the CARD domains of MAVS and RIG, ultimately leading to the formation of MAVS aggregates." (PMID 40040697, 2025). "Mitochondrial antiviral signaling protein (MAVS), a vital MAMs-associated protein and a key player in the innate immune response, was shown to recruit NLRP3 to mitochondria during viral infection and promoted inflammasome activation." (PMID 41367495, 2025). "Desuccinylation by SIRT5 at the K7 site reduces the formation of MAVS aggregates after viral infection, leading to inhibition of MAVS activation and downregulation of the body’s antiviral capacity." (PMID 39979670, 2025). "OAS1 and MAVS are Interferon Stimulated Genes (ISGs) which are up-regulated during active viral infections." (PMID 41468475, 2025). "This indicated that the function of some E3 ligases (e.g., Smurf1) to interact and degrade MAVS is enhanced in the early and middle stages of viral infection." (PMID 39665545, 2025). "The interaction of the CARD domain is a key step in MAVS signal transduction, determining its responsiveness to viral infections." (PMID 40842475, 2025). "In the context of viral infection, the activation of MAVS (mitochondrial antiviral-signaling protein) has been associated with the subsequent activation of the JNK pathway." (PMID 40968155, 2025).
viral infection (continued). "Mitochondrial antiviral signaling (MAVS) is a protein located on the outer mitochondrial membrane that plays a crucial role in the induction of the host’s innate immune response to viral infections." (PMID 38338917, 2024). "Ever-increasing amounts of evidence have demonstrated that the induction of mitophagy upon virus infection suppresses mitochondria-mediated antiviral innate immune response by degrading MAVS." (PMID 38443986, 2024). "Here, we provided several lines of evidence to demonstrate that DDX11 acted as a co-receptor to promote viral RNA binding to RIG-Ι, and the interaction of RIG-Ι and MAVS upon viral infection." (PMID 39470258, 2024). "It is well established that ROS-based MAVS aggregation generated by virus infection, chemicals, or systemic lupus erythematosus facilitates type I IFN signaling." (PMID 39282299, 2024). "DHX29 activates the RIG-I/MAVS-dependent signaling pathway, making it important for immune responses and potential drug/vaccine design against viral infections." (PMID 38513890, 2024). "Cytoplasmic glutamine-proline tRNA synthetase acts bi-directionally in viral infections to complex with mitochondrial antiviral-signaling protein to protect it from degradation thereby enhancing viral clearance." (PMID 39039092, 2024). "Upon viral infection, MAVS undergoes ubiquitination, which is a critical event for regulating MAVS aggregation." (PMID 39621307, 2024). "Rig-I, MDA5, and members of DExD/H-box RNA helicases including DHX15 that recognize dsRNA and these receptors signal via MAVS which isa critical downstream adaptor in RLR signaling that drives the innate response to virus infection." (PMID 39772220, 2024). "The interaction of MAVS with TRAF3/6 plays a crucial role in various viral infection mechanisms by activating the IRF3, IRF7, and NF-kB pathways." (PMID 38995016, 2024). "In summary, these siRNA silencing results confirm that TRAF1 negatively regulates virus infection and release by interacting with the MAVS protein and is involved in the RIG-I pathway." (PMID 38995016, 2024). "As a pivotal member of the RLR pathway, TRAF3 is essential for activating the MAVS/TBK-1/IRF3 signaling pathway in response to viral infection." (PMID 39058724, 2024). "As a key adaptor protein in the RLR signaling pathway, MAVS forms unique prion-like aggregation that serves as a platform for efficient signaling propagation upon virus infection." (PMID 39141356, 2024). "Here, we demonstrated that the palmitoylation of MAVS at cysteine 79 (C79), which is catalyzed mainly by the palmitoyl S-acyltransferase ZDHHC12, was essential for MAVS aggregation and antiviral innate immunity upon viral infection in macrophages." (PMID 39621307, 2024). "The mitochondrial adaptor protein MAVS is also known to form prion-like aggregates in response to viral infection to elicit antiviral innate immunity." (PMID 39194237, 2024). "It interacts with myeloid differentiation primary response 88 (MyD88) and mitochondrial antiviral-signaling protein (MAVS), which are pivotal adaptor proteins involved in innate immune signaling pathways activated by viral infections." (PMID 38747288, 2024). "After viral infection, these receptors recruit downstream molecules, including MAVS, TBK1, or RIP2 to activate IRF3, a common molecule in all innate immune signaling pathways." (PMID 38516932, 2024). "These proteins activate the interferon signaling pathway by recognizing viral infections and interacting with the mitochondrial antiviral signaling protein (MAVS)." (PMID 38465233, 2024). "We also showed interaction of the N-protein with the mitochondrial protein MAVS, which plays a crucial role in antiviral responses, and signals the immune system by activating pro-inflammatory cytokines to combat viral infections within cells." (PMID 39375263, 2024).
viral infection (continued). "IRF1 is an ISG that is present in all types of cells before viral infection and activates the downstream MAVS pathway; it is only involved in the transcription of the IFN-λ gene and not in the gene induction of type I IFN." (PMID 38495892, 2024). "We have previously showed that upon activation, RIG-I and MDA5 relocalize to mitochondria-associated membrane (MAM) to interact with MAVS, which is the crucial onset of MAVS-mediated IFN production pathway during acute phase of viral infection." (PMID 38843304, 2024). "Chen and colleagues (2020) revealed that MAVS and Drp1 not only interact with each other but also have a strong affinity when detecting RNA, which can appear in the cytosol during viral infection." (PMID 39338909, 2024). "It is well documented that upon virus infection, the MDA5 CARDs domain undergoes K63-linked polyubiquitination and recruits MAVS to form a signalosome." (PMID 37956198, 2023). "After viral infection, RNF115 disassociates from MAVS and catalyzes the K63-linked ubiquitination of STING at K20, K224, and K289, thereby promoting MAVS translocation to the ERGIC and the recruitment of TBK183." (PMID 36964253, 2023). "This yielded two candidate drugs, pibrentasvir (predicted by FRAGSITE2) and atovaquone (predicted by other in silico methods), which were MAVS-dependent and acted early during viral infections." (PMID 37766247, 2023). "Viral infection leads to MAVS cleavage and combined with fluorescence relocalization, these systems are sensitive and convenient to indicate enterovirus infection in live cells." (PMID 37243150, 2023). "The potential use of miRNAs and MAVS as therapeutic agents holds promise for the treatment of viral infections and other diseases." (PMID 37901251, 2023). "have reported that MAVS mediates NF-κB and type I interferon signaling during viral infection and is also required to activate the NLR family pyrin domain containing 3 (NLRP3) that triggers an immune response.." (PMID 38187378, 2023). "During viral infection, the adaptor proteins MAVS and STING are phosphorylated by the kinase IKK/TBK1 in response to stimulation, inducing type I interferons (IFNs) and other antiviral molecules." (PMID 37143582, 2023). "It has been shown to promote the degradation of MAVS through ubiquitination, thereby dampening the downstream signaling events triggered by MAVS during viral infections." (PMID 38250078, 2023). "Mitochondrial antiviral signaling protein (MAVS) is an innate immune adaptor on the outer mitochondrial membrane that acts as a switch in the immune signal transduction response to viral infections." (PMID 38187378, 2023). "It has been reported that the N-terminal truncated proteoform of MAVS we have identified becomes the dominant expressed MAVS proteoform upon viral infection." (PMID 37316325, 2023). "Mitochondrial antiviral signaling protein (MAVS), associated with the outer mitochondrial membrane, mediates the activation of NFK-B and the induction of interferons in response to viral infection." (PMID 36151435, 2023). "In contrast, in HIV-1, VSV, and ZIKV, SERINC5 inhibits virus infection by interacting with the outer mitochondrial membrane protein MAVS facilitating its aggregation and, consequently, triggering the activation of downstream signaling pathways." (PMID 36876111, 2023). "Some studies have reported that MAVS mediates NF-κB and type I interferon signaling during viral infection and is also required for optimal NLRP3 inflammasome activity." (PMID 37901251, 2023). "Activating the immune response through mitochondrial antiviral signaling (MAVS), a protein located on the outer mitochondrial membrane, is essential for the innate immunity against viral infections." (PMID 37351502, 2023). "MicroRNA-125a has been reported to target the MAVS 3’-UTR during viral infection, negatively regulating the antiviral response by inhibiting MAVS expression, leading to reduced production of type I interferons." (PMID 37901251, 2023).
viral infection (continued). "Conversely, the regulation of RNF5 and its interaction with STING and MAVS presents potential therapeutic avenues for modulating immune responses and combating viral infections." (PMID 38250078, 2023). "As an adaptor, SARM has been reported that interact with the mitochondrial antiviral-signaling protein MAVS in the mitochondria to mediate cell death during virus infection." (PMID 36817462, 2023). "Since MAVS acts as a downstream-signaling intermediary of the two cytosolic dsRNA sensors MDA5 and RIG-I, compounds which inhibit viral infections via nsp15 should be MAVS-dependent." (PMID 37766247, 2023). "Mitochondrial antiviral signaling protein (MAVS) is a key innate immune adaptor on the outer mitochondrial membrane that acts as a switch in the immune signal transduction response to viral infections." (PMID 37901251, 2023). "Through direct protein-protein interaction, WDR77 represses the prion-like aggregation of MAVS, thereby negatively regulating MAVS activity after viral infection." (PMID 37563140, 2023). "As the only decrease in antiviral proteins follows viral infection, the mechanism by which MAVS regulates the innate immune response to the YT strain merits further research." (PMID 37063902, 2023). "Mitophagy has been shown to regulate mtROS production during viral infection, promoting the RLRs-MAVS signaling." (PMID 37325622, 2023). "We next investigated the role of WDR77 in the regulation of MAVS aggregation over time, and we performed a time course analysis of MAVS aggregation following virus infection." (PMID 37563140, 2023). "Through its involvement in these intricate signaling cascades, MAVS contributes to the clearance of viral infections and maintenance of immune homeostasis." (PMID 37901251, 2023). "MAVS also physically interacts with the NLRP3, and it has been suggested that MAVS is required for the NLRP3 inflammasome activation by viral infections." (PMID 37692170, 2023). "Following viral infection, MAVS (mitochondrial antiviral signaling protein)-mediated E3 ligase TRAF3 recruitment leads to K63 polyubiquitination of ASC via autophagy, leading to its degradation." (PMID 37465127, 2023). "Our previous study showed that TRIM21, by catalyzing the K27-linked ubiquitination of mitochondrial antiviral signaling protein (MAVS), augments RIG-I/MDA5-mediated transcription of IFNs upon viral infection." (PMID 37327222, 2023). "Taken together, these results suggest that the interaction of N protein and UBC9 plays a crucial role in regulating the SUMOylation and ubiquitination modifications of MAVS during virus infection." (PMID 38140545, 2023). "Surprisingly, in both cell types the levels of MAVS protein increased when those of SERINC5 decreased during viral infection, suggesting the involvement of a SERINC5-independent and positive regulatory mechanism of MAVS." (PMID 36876111, 2023). "It has been shown to reduce MAVS-mediated inflammation and immune response in various viral infection models." (PMID 37901251, 2023). "For RIG-I, the N-terminal CARD domain mediates its interaction with downstream MAVS upon viral infection, and with STATs upon cytokine stimulation determined here and in our previous study." (PMID 36333807, 2022). "Deletion of the mitochondrial fusion regulators MFN1 and MFN2 abrogates the MAVS-IFN-I signaling pathway during viral infection." (PMID 35073751, 2022). "Although MAVS is widely studied for mediating the activation of NF-κB and IRF3 in response to viral infection, MAVS also plays a critical role in central nervous system inflammation and metabolism." (PMID 35850307, 2022). "Stimulation of RLRs with dsRNA or viral infection induces MAVS-dependent ubiquitination of IRF3 and subsequent activation of pro-apoptotic factors independent of IRF3’s transcriptional activity." (PMID 35436994, 2022).
viral infection (continued). "While apoptosis and IFN-I mediated by mitochondrial antiviral signaling (MAVS) are well-established defenses, new dimensions of mitochondrial biology are emerging as battlefronts during viral infection." (PMID 35073751, 2022). "The mitochondrial membrane‐associated protein MAVS serves as a core adaptor protein for RLR signaling and is essential for controlling viral infection." (PMID 37521851, 2022). "Viral infection causes the IRF3/7-dependent induction of OTUD4, which binds to MAVS to cleave K48-conjugated ubiquitin chains, stabilizing MAVS and activating antiviral innate immune responses." (PMID 36411454, 2022). "The mitochondrial antiviral-signaling protein (MAVS) is located in the outer mitochondrial membrane and serves as an important signaling platform in viral infections." (PMID 36300112, 2022). "Upon RIG-I activation, MAVS is activated in the early stages of viral infection, activating IKKα/IKKβ/NEMO in a CARMA3-dependent manner." (PMID 36618379, 2022). "The study found that the expression of E3 MARCH5 is up-regulated during virus infection, and it can catalyze the ubiquitination of K7, and K500 residues of MAVS to mediate the proteasomal degradation of MAVS." (PMID 36505476, 2022). "In response to viral infection, MAVS, a membrane-bound protein, transmits signals from RIG-I to downstream signaling molecules via the transcription factors NF-B, IRF3, and IRF7 to create inflammatory cytokines such as IFN-beta." (PMID 36776376, 2022). "Prion-like aggregation of MAVS is required for its activation, which presumably releases its autoinhibition on the amino acids 360–540 of MAVS after a viral infection." (PMID 35820905, 2022). "RNA viruses also hijack MAVS degradation mechanisms to facilitate viral replication and viral infection." (PMID 35795661, 2022). "In contrast, RIG-I and MAVS are phosphorylated at resting states and upon viral infection; removal of phosphorylation on RIG-I and MAVS by PP1α and PP1γ is required for their activation." (PMID 35795661, 2022). "A subsequent study demonstrated that this interaction promotes redistribution of MAVS to speckle-like patterns on mitochondria and impacts MAVS signaling in response to viral infection and transfected 5’ppp-RNA." (PMID 35073751, 2022). "The centrality of MAVS in the response of microglia to RVFV in vitro is clear, with equivalent levels of viral infection inducing an extremely attenuated response in MAVS-deficient cells." (PMID 35584192, 2022). "TRIM31 catalyzes the K63-linked polyubiquitylation of MAVS at the K10/311/461 sites, promotes its aggregation, and increases IFN-β production, thereby inhibiting virus infection." (PMID 36498930, 2022). "Activated RIG‐I and mitochondrial antiviral signaling (MAVS) protein trigger a series of corresponding immune responses such as the production of type I interferon against viral infection." (PMID 37521851, 2022). "Further, the interaction between endogenous PRMT9 and MAVS was found to be attenuated upon viral infection." (PMID 36028484, 2022). "We next examined key molecules in the RIG‐I pathway and found that TBK1 and IRF3 phosphorylation was severely compromised in response to viral infection despite restoration of MAVS level following protease inhibitors treatment." (PMID 36216581, 2022). "Viral infections induce the accumulation and aggregation of signature molecules known as mitochondrial antiviral-signaling proteins (MAVS) on the mitochondrial outer membrane (OMM)." (PMID 35903542, 2022). "Following viral infection, MAVS undergoes a conformational switch that leads to the formation of prion-like functional aggregates on the mitochondrion." (PMID 35171955, 2022). "Mitochondrial antiviral signaling (MAVS) is known as an innate immune regulator involved in viral infectious diseases and autoimmune diseases, whereas its role in the heart remains obscure." (PMID 35844503, 2022).